JPT1 (Jupiter microtubule associated homolog 1)
Description:
Modulates negatively AKT-mediated GSK3B signaling. Induces CTNNB1 'Ser-33' phosphorylation and degradation through the suppression of the inhibitory 'Ser-9' phosphorylation of GSK3B, which represses the function of the APC:CTNNB1:GSK3B complex and the interaction with CDH1/E-cadherin in adherent junctions. Plays a role in the regulation of cell cycle and cell adhesion. Has an inhibitory role on AR-signaling pathway through the induction of receptor proteasomal degradation.
Synonyms: ARM2; HN1; HN1A
Tractability: PROTAC: ubiquitination databases record sites on it.
Gene: Protein-coding gene on chromosome 17 (75,135,248 to 75,168,281, reverse strand). Ensembl gene ENSG00000189159.
Subcellular location: Nucleus; Cytoplasm
Subcellular location (Human Protein Atlas): Cytosol; Cytokinetic bridge; Microtubules; Nucleoplasm
Gene Ontology:
Molecular function: protein binding
Cellular component: cytoplasm; cytosol; nucleoplasm; nucleus
Genetic constraint (gnomAD): Loss-of-function variants: 4 observed, 12.31 expected, observed/expected ratio (o/e) 0.32, 90% interval 0.16 to 0.74. The upper end of that interval is the gene's LOEUF score, 0.74, which puts it in group 3 of 6, group 1 being the genes least tolerant of losing a copy. Missense variants: 147 observed, 177.93 expected, observed/expected ratio (o/e) 0.83, 90% interval 0.72 to 0.95. Synonymous variants: 69 observed, 71.61 expected, observed/expected ratio (o/e) 0.96, 90% interval 0.79 to 1.18.
Homologues: Orthologues: pig JPT1 (92% identical), rabbit JPT1 (92% identical), mouse Jpt1 (90% identical), rat Jpt1 (88% identical), guinea pig JPT1 (79% identical), tropical clawed frog jpt1 (44% identical).
Diseases named in the same sentence as JPT1 in open-access papers:
JPT1 is named in the same sentence as 5 diseases in open-access papers, as found by Europe PMC text mining. Sharing a sentence is not in itself a finding about the gene and the disease. The quoted sentences say what the papers report.
endometrial cancer (2 papers, 2020 to 2023). Primary or metastatic malignant neoplasm involving the endometrium (mucous membrane that lines the endometrial cavity). "We report JPT1 (Jupiter microtubule‐associated homolog 1) as a predictive and pharmacodynamic biomarker candidate of metformin response in endometrial cancers." (PMID 31808620, 2020). "Metformin response and loss of JPT1 were assessed in RL95‐2 and ACI‐181 endometrial cancer (EC) cell lines." (PMID 31808620, 2020). "In addition, among the genes closely associated with PPP1R14B expression, UBE2S, JPT1, and PTTG1 were associated with abnormal expression of endometrial cancer desiccations, proliferation, migration, methylation, and prediction of response to metformin therapy." (PMID 36824011, 2023).
prostate tumour (1 paper, 2024). "On the other hand, circular LPAR3 RNA targets Jupiter microtubule-associated homolog 1 (JPT1) to decrease the radiosensitivity of prostate tumour cells." (PMID 38607068, 2024).
cancer (5 papers, 2019 to 2025). A tumor composed of atypical neoplastic, often pleomorphic cells that invade other tissues. "Previous studies have reported that UTP6 participates in pre-18S ribosomal RNA (rRNA) processing within the nucleolus, while HN1, also known as JPT1, regulates cell migration in carcinomas including breast and prostate cancer." (PMID 40917497, 2025). "JPT1 (HN1) promotes cancer metastasis via activating the nuclear factor κB (NF-κB) signaling pathway." (PMID 36542699, 2022). "Here, we discovered that 3′ UTR of HN1 (or JPT1) showed shortening in cancers and lengthening in senescence, correlated well with its high expression in cancer cells and low expression in senescent cells, respectively." (PMID 31257225, 2019). "Second, different proteoforms from the same cancer-related gene (e.g., DAP, CALM1, HDGF, JPT1, RALY, and NPM1) may have potentially varied biological functions in modulating CRC metastasis, because they show opposite expression profiles between the SW480 and SW620 cells." (PMID 36542699, 2022).
tumor (2 papers, 2020 to 2024). "We further assessed the correlation of JPT1 and MKI67 transcript expressions using a public RNA‐seq dataset established from 540 EC patient's tumor tissues, and found that these genes were positively correlated in EC patient tissues (Spearman = 0.37, P < .0001)." (PMID 31808620, 2020).
JPT1 also shares sentences with these, for which no sentence is quoted: breast carcinoma (1 paper).